PPP1R3B (protein phosphatase 1 regulatory subunit 3B)
Description:
Acts as a glycogen-targeting subunit for phosphatase PP1. Facilitates interaction of the PP1 with enzymes of the glycogen metabolism and regulates its activity. Suppresses the rate at which PP1 dephosphorylates (inactivates) glycogen phosphorylase and enhances the rate at which it activates glycogen synthase and therefore limits glycogen breakdown. Its activity is inhibited by PYGL, resulting in inhibition of the glycogen synthase and glycogen phosphorylase phosphatase activities of PP1. Dramatically increases basal and insulin-stimulated glycogen synthesis upon overexpression in hepatocytes (By similarity).
Synonyms: PTG; PPP1R4; GL; FLJ14005
Tractability: Small molecule: it has a binding pocket of medium quality. PROTAC: ubiquitination databases record sites on it.
Gene: Protein-coding gene on chromosome 8 (9,136,255 to 9,151,574, reverse strand). Ensembl gene ENSG00000173281.
Subcellular location (Human Protein Atlas): Cytosol
Gene Ontology:
Molecular function: protein binding; glycogen binding; protein phosphatase 1 binding; [phosphorylase] phosphatase activity; enzyme binding; phosphoprotein phosphatase activity; protein phosphatase regulator activity
Biological process: negative regulation of glycogen catabolic process; regulation of glycogen biosynthetic process; positive regulation of glycogen biosynthetic process; regulation of glycogen catabolic process
Cellular component: protein phosphatase type 1 complex; glycogen granule
Genetic constraint (gnomAD): Loss-of-function variants: 12 observed, 21.41 expected, observed/expected ratio (o/e) 0.56, 90% interval 0.36 to 0.91. The upper end of that interval is the gene's LOEUF score, 0.91, which puts it in group 3 of 6, group 1 being the genes least tolerant of losing a copy. Missense variants: 452 observed, 378.91 expected, observed/expected ratio (o/e) 1.19, 90% interval 1.1 to 1.29. Synonymous variants: 169 observed, 149.11 expected, observed/expected ratio (o/e) 1.13, 90% interval 1 to 1.29.
Homologues: Orthologues: chimpanzee PPP1R3B (99% identical), macaque PPP1R3B (96% identical), pig PPP1R3B (90% identical), rabbit PPP1R3B (90% identical), dog PPP1R3B (90% identical), guinea pig PPP1R3B (90% identical), mouse Ppp1r3b (89% identical), rat Ppp1r3b (89% identical), tropical clawed frog ppp1r3b (62% identical), zebrafish ppp1r3b (51% identical), Drosophila melanogaster Gbs-70E (32% identical), Caenorhabditis elegans H18N23.2 (28% identical). Paralogues in human: PPP1R3C (42% identical), PPP1R3A (27% identical), PPP1R3D (26% identical), PPP1R3F (24% identical), PPP1R3G (22% identical), PPP1R3E (20% identical).
Diseases named in the same sentence as PPP1R3B in open-access papers:
PPP1R3B is named in the same sentence as 34 diseases in open-access papers, as found by Europe PMC text mining. Sharing a sentence is not in itself a finding about the gene and the disease. The quoted sentences say what the papers report.
Hepatic steatosis (9 papers, 2017 to 2025). Steatosis is a term used to denote lipid accumulation within hepatocytes. "Among AA in our MVP cohort, significant associations with NAFLD and/or ALT were detected for 6 variants, including PNPLA3 (rs738409) and PPP1R3B (rs4240624), which were previously reported in 3,124 AA patients examined for hepatic steatosis by CT." (PMID 32841307, 2020). "In 125 liver biopsy samples from obese patients, the rs4841132-A allele (vs. G) was associated with higher PPP1R3B mRNA levels and reduced LOC157273 expression and protection against histologic hepatic steatosis." (PMID 32754192, 2020). "These TAGs are additionally associated with higher consumption of carbohydrate and saturated fat, hepatic steatosis, and variations in the gene for protein phosphatase 1, regulatory subunit 3b (PPP1R3B), which in part regulates glycogen synthesis." (PMID 29925420, 2018). "PPP1R3B rs4240624 is associated with CT-diagnosed hepatic steatosis, but not histological evidence of inflammation and fibrosis and the PPP1R3B rs61756425 variant is a strong predictor of severe NAFLD on ultrasound (OR: 32.6, 95% CI 4.22–251.4, p = 0.001)." (PMID 31969816, 2019). "Finally, we found a significant association between the PPP1R3B rs61756425 and MBOAT7 rs641738 variants in predicting the severity of hepatic steatosis." (PMID 29487372, 2018). "A NGS-identified variant in PPP1R3B gene (rs61756425 G/T p.S41R) emerged as more frequent in NAFLD patients than in controls (χ2 = 16.11, P < 0.001) and as the strongest independent genetic predictor of severe hepatic steatosis (OR = 32.6, 95% CI, 4.22-251.4, Padj = 0.001)." (PMID 29487372, 2018). "The protein phosphatase 1 regulatory subunit 3B gene (PPP1R3B), which associated with liver attenuation, did not associate with MASLD histology and was subsequently shown to promote liver glycogen storage, as opposed to hepatic steatosis, both of which affect liver attenuation." (PMID 40166930, 2025).
Insulin resistance (5 papers, 2019 to 2025). Increased resistance towards insulin, that is, diminished effectiveness of insulin in reducing blood glucose levels. "Four of these loci, all not previously implicated in post-challenge insulin resistance, were significantly associated with IFC (N = 52,474; SLC2A4, PPP1R3B, C2CD4A and MTNR1B)." (PMID 37291194, 2023).
liver disease (5 papers, 2016 to 2021). "Recently, the Hydroxysteroid 17-Beta Dehydrogenase 13 (HSD17B13) rs7261356 and the Protein Phosphatase 1 Regulatory Subunit 3B (PPP1R3B) rs4841132 have been shown to confer protection against liver disease, at least in at-risk individuals, instead." (PMID 32443539, 2020). "Based on this evidence, the role of PPP1R3B rs61756425 variant in liver disease surely requires additional evaluation with a direct confirmation of liver histological changes associated with this variant." (PMID 29487372, 2018). "An alternative protective player against hepatic disorders is exemplified by the rs4841132 G > A variation, which strengthens the expression of the Protein Phosphatase 1 Regulatory Subunit 3B (PPP1R3B) gene, involved in glycogenesis." (PMID 34680476, 2021). "Finally, the rs4841132 G>A variant, enhancing the expression of Protein Phosphatase 1 Regulatory subunit 3B (PPP1R3B), which is involved in glycogen synthesis, has been recently reported to reduce the risk of NAFLD, but at the same time, may favor liver disease by facilitating glycogen accumulation." (PMID 32340286, 2020).
atherosclerosis (4 papers, 2016 to 2025). A disease characterized by the build-up of fatty material and calcium deposition in the arterial wall resulting in partial or complete occlusion of the arterial lumen. "Furthermore, the PPP1R3B variants were found to influence cardiovascular events and atherosclerosis." (PMID 29681992, 2018). "Nonetheless, further investigation is warranted to fully assess and exclude any potential roles of PPP1R3B in non‐MΦ populations, especially in advanced atherosclerosis or metabolic disorders." (PMID 40984828, 2025). "In addition, we evaluated the potential relationship between HNF1A rs1183910, LEPR rs4420065, GCKR rs1260326, NLRP3 rs12239046, IL1F10 rs6734238, PPP1R3B rs9987289, ASCL1 rs10745954, HNF4A rs1800961 and SALL1 rs10521222 polymorphisms and CV events or subclinical atherosclerosis in RA patients." (PMID 27534721, 2016).
Obesity (4 papers, 2016 to 2024). Accumulation of substantial excess body fat. "We also identified signals of recent positive selection on chromosome 8p23.1, and one gene within this locus, PPP1R3B, is related to glycogenesis and has been associated with an increased risk of type 2 diabetes and obesity." (PMID 31554886, 2019).
type 2 diabetes (4 papers, 2019 to 2021). "PPP1R3B has been suggested as a candidate gene for monogenic forms of diabetes as well as type 2 diabetes (T2D) due to its association with glycaemic trait and its biological role in glycogen synthesis." (PMID 30629617, 2019).
diabetes (3 papers, 2019 to 2024). "Mechanistically, hepatic mTORC1 activity promotes the feeding-dependent induction of Ppp1r3b, a gene encoding a phosphatase important for glycogen synthase activity whose polymorphisms are linked to human diabetes." (PMID 38290087, 2024). "The PPP1R3B is located on 8p23.1 which has been linked with T2D and monogenic diabetes." (PMID 30629617, 2019). "Indeed, evidence for common genetic variation in PPP1R3B itself has been inconsistent for T2D risk in humans, although rare variants in PPP1R3B are associated with human diabetes phenotypes." (PMID 32754192, 2020). "PPP1R3B has long been an attractive target for diabetes therapy, based on the concept of tipping ambient glycemic balance toward hepatic glycogen deposition." (PMID 32754192, 2020). "The chr8p23.1 variant rs4841132, associated with an insulin-resistant diabetes risk phenotype, lies in the second exon of a long non-coding RNA (lncRNA) gene, LOC157273, located 175 kilobases from PPP1R3B, which encodes a key protein regulating insulin-mediated hepatic glycogen storage in humans." (PMID 32754192, 2020). "Furthermore, carriers with diabetes had less abdominal fat and a higher serum concentration of LDL-cholesterol compared to patients with T2D without rare missense PPP1R3B variants." (PMID 30629617, 2019).
coronary artery disease (2 papers, 2018 to 2022). "Little is known about the association of the protein phosphatase 1 regulatory subunit 3B gene (PPP1R3B) single nucleotide polymorphisms (SNPs) and serum lipid levels, the risk of coronary artery disease (CAD) and ischemic stroke (IS) in the Chinese populations." (PMID 29681992, 2018).
non-alcoholic fatty liver disease (2 papers, 2018 to 2019). "PPP1R3B variants such as rs4240624 have previously been associated not only with lipid concentrations but also with histologic non-alcoholic fatty liver disease (NAFLD) which is characterized by increased hepatic triglyceride content." (PMID 30629617, 2019). "Several previous studies have also found the association of variants in PPP1R3B locus with other cardiometabolic risk factors such as fasting glucose, fasting insulin, ferritin, liver enzymes, and nonalcoholic fatty liver disease." (PMID 29681992, 2018).
steatosis (2 papers, 2020 to 2025). Increased lipid within the cytoplasm of cells. "The specificity of variant-metabolite associations were compared to metabolite associations with ultrasound-defined steatosis, gene variants linked to liver fat (in GCKR, PPP1R3B and LYPLAL1) and gene variants linked to cirrhosis (in HFE and SERPINA1)." (PMID 32720691, 2020).
dyslipidemia (1 paper, 2018). "Detection of these PPP1R3B SNPs in our study population may have important significance for early diagnosis and future individualized treatment of dyslipidemia, CAD and IS." (PMID 29681992, 2018).
lung carcinoma (1 paper, 2024). "Loss-of-function genetic mutations in PPP1R3B gene have been associated with lung cancer, similarly, DNA methylation associated transcription silencing mimics loss-of-function properties." (PMID 38475971, 2024).
MODY (1 paper, 2019). "Nevertheless, based on our findings, the linkage peak with MODY cannot be explained by the PPP1R3B variants found in the present study, and the association with T2D of the variants identified in the present study is insufficient to explain the T2D linkage peak." (PMID 30629617, 2019). "Among n = 396 carriers, we identified twenty-three PPP1R3B missense mutations, none of which segregated with MODY." (PMID 30629617, 2019). "Targeted resequencing of PPP1R3B was performed in 8,710 samples; MODY patients with unknown etiology (n = 54), newly diagnosed patients with T2D (n = 2,930) and population-based control individuals (n = 5,726, of whom n = 4,569 had normal glucose tolerance)." (PMID 30629617, 2019).
oesophageal cancer (1 paper, 2024). "We observed one individual with oesophageal cancer phenotype harbouring an epimutation at the PPP1R3B promoter." (PMID 38475971, 2024).
osteoarthritis (1 paper, 2024). A noninflammatory degenerative joint disease occurring chiefly in older persons, characterized by degeneration of the articular cartilage, hypertrophy of bone at the margins and changes in the synovial membrane. "Previous GWASs have found that PPP1R3B variants affect bone mineral density (BMD) and genetic susceptibility to osteoarthritis." (PMID 39199755, 2024).
cancer (4 papers, 2015 to 2025). A tumor composed of atypical neoplastic, often pleomorphic cells that invade other tissues. "Using the criteria of circadian proteomic expression, circadian expression in multiple tissues and independent gene knockdown data, we propose six genes (Por, Mtss1, Dgat2, Pim3, Ppp1r3b, Upp2) involved in metabolism and cancer for further experimental investigation." (PMID 26576534, 2015). "Other KDs were associated with signal transduction and kinase activity (PRKCA, TAOK1, and ADRBK1), membrane transport (SLC9A3R1), metabolism (PPP1R3B), gene regulation (USF1), and immune responses and cancer (SLAMF8, SRC, and KIAA0100)." (PMID 41402937, 2025).
infection (2 papers, 2022 to 2025). The state of being infected such as from the introduction of a foreign agent such as serum, vaccine, antigenic substance or organism. "Another of the up-regulated genes, PPP1R3B was up-regulated at both 6hpi and 12hpi during infection with the New York strain." (PMID 36204651, 2022). "Furthermore, we confirmed the downregulation of ppp1r3b and detected a positive correlation between its expression and hepatic glycogen during infection, indicating that GR signaling helps to maintain glycogen levels." (PMID 40702267, 2025).
PPP1R3B also shares sentences with these, for which no sentence is quoted: cardiovascular disease (2 papers); tumor (2); breast carcinoma (1); breast tumors (1); cat-eye syndrome (1); Cirrhosis (1); Crohn disease (1); Glucose intolerance (1); Hepatic fibrosis (1); hepatoma (1); Hyperinsulinemia (1); ischemic stroke (1); metabolic disorders (1); non-alcoholic steatohepatitis (1); psoriatic arthritis (1); rheumatoid arthritis (1); viral infections (1).